CD38 (CD38 molecule)
Diseases named in the same sentence as CD38 in open-access papers (continued):
Sharing a sentence is not in itself a finding about the gene and the disease.
airway hyperresponsiveness (11 papers, 2008 to 2024). "CD38 deficiency remarkably impeded the airway hyperresponsiveness of asthmatic mice." (PMID 32889801, 2020). "Cytokines such as IL-13 or TNF-α caused significantly lower inflammation and hyperresponsiveness in the CD38 KO mice compared to WT controls, suggesting the crucial roles of CD38 in the contractility of airway smooth muscle and airway hyperresponsiveness." (PMID 30619097, 2018). "Previous results have shown that CD38, involved in generating calcium mobilizing molecules, contributes to airway hyperresponsiveness." (PMID 26998837, 2016). "CD38−/− mice develop attenuated airway hyperresponsiveness following allergen or cytokine challenge." (PMID 25175907, 2014). "The airway hyperresponsiveness following cytokine challenge or allergen sensitization and challenge is significantly compromised in CD38−/− mice." (PMID 23213344, 2012). "CD38 also contributes to airway hyperresponsiveness as shown in mouse models of allergen or cytokine-induced inflammatory airway disease." (PMID 23213344, 2012). "Therefore, further studies are needed to detect the regulatory effect of PTEN/CD38 axis on the airway function, such as airway hyperresponsiveness." (PMID 32889801, 2020). "Therapeutic strategies that target both CD38 and these miRNA networks may prove effective in reversal of allergen-induced changes in airway hyperresponsiveness and airway inflammation, particularly in the asthmatic patient." (PMID 26998837, 2016). "The overexpression of CD38 could augment cADPR and SR Ca2+ release favoring airway hyperresponsiveness." (PMID 27445440, 2016). "Furthermore, CD38−/− mice exhibit attenuated methacholine responsiveness and airway hyperresponsiveness (AHR) following allergen sensitization and challenge as well as after intranasal IL-13 challenge." (PMID 25175907, 2014). "TNFα/IFNγ augmented the expression of several genes that were also corticosteroid insensitive including, CD38, a Ca2+ regulatory protein that contributes to ASM hypercontractility and airway hyperresponsiveness." (PMID 35578269, 2022).
Alzheimer disease (11 papers, 2013 to 2026). A progressive, neurodegenerative disease characterized by loss of function and death of nerve cells in several areas of the brain leading to loss of cognitive function such as memory and language. "Indeed, previous studies have found that the loss of CD38 enzymatic function was protective against Alzheimer’s Disease (AD) pathologies in a model of AD-prone CD38-deficient mice." (PMID 35712720, 2022). "CD38 dysregulation and gene variation is reported in neurodegenerative conditions such as Parkinson's disease (PD) and Alzheimer's disease (AD), highlighting the need to better understand CD38 biology within the brain." (PMID 41400119, 2026). "Studies in a mouse model of Alzheimer’s disease have shown that aerobic exercise upregulates CD38 expression in astrocytes, facilitating the CD38-mediated transfer of healthy mitochondria from astrocytes to neurons." (PMID 40943622, 2025). "Our analysis identifies specific subgroups of immune cells including CD38 on IgD- CD38br, IgD on IgD + CD24+, IgD on IgD + CD38br,IgD on IgD+, as potential risk factors for Alzheimer’s disease through Mendelian randomization analysis." (PMID 38500057, 2024). "Second, the CSF levels of mi-RNA-708 and miRNA-140-3p, which were shown to reduce CD38 expression in vitro, are significantly decreased by nearly 4- and 2.5-fold, respectively, in Alzheimer’s disease patients compared to age-matched controls." (PMID 32085567, 2020). "In Alzheimer’s disease, CD38 immunoreactivity was observed in intracellular tangles and neuropil threads." (PMID 32085567, 2020). "The NAD+ degrading enzyme CD38 levels increase during aging, may regulate Alzheimer’s disease pathology, and play a role in neuroinflammation." (PMID 39199312, 2024). "Mendelian randomization analyses suggested causal roles for several proteins, for example, ApoE, CD33, and GRN in Alzheimer's disease, MMP‐10 in preclinical Alzheimer's disease, SIGLEC9 in amyotrophic lateral sclerosis, and CD38, GPNMB, and ADAM15 in Parkinson's disease." (PMID 36504281, 2023).
neutropenia (11 papers, 2021 to 2025). A decrease in the number of neutrophils found in the blood. "Regarding safety, the profile of isatuximab is characterized by an increased risk of grade ≥ 3 neutropenia and infections such as pneumonia, effects consistent with the immunomodulatory actions of anti-CD38 antibodies." (PMID 41228289, 2025). "The MAbs targeting SLAMF7 group had a lower risk of neutropenia than the MAbs targeting PD-1/ PD-L1 and CD38 groups." (PMID 34488679, 2021). "In addition, the SLAMF7 group prolonged PFS compared with the PD-1/PD-L1 group and was associated with a lower incidence of grade 3 or higher neutropenia than the CD38 and PD-1/PD-L1 group." (PMID 34488679, 2021). "MM cell markers, including BCMA and CD38, were also coexpressed on normal B lymphocytes; therefore, anti-BCMA antibody-based immunotherapy could also result in B-cell aplasia, neutropenia, and immunosuppression, leading to increased infection risks." (PMID 39025844, 2024). "The RR for neutropenia of the CD38 group vs SLAMF7 group was 1.818 (95%CI 1.41–2.344)." (PMID 34488679, 2021). "Similarly, in the frail subgroup of the ALCYONE trial, higher rates ≥ grade 3 neutropenia (41.3% Dara-VMP vs. 34.4% VMP) and infection (30.0% Dara-VMP vs. 17.9% VMP) were observed with the addition of the anti-CD38 antibody." (PMID 36599867, 2023).
non-Hodgkin lymphoma (11 papers, 2013 to 2026). Distinct from Hodgkin lymphoma both morphologically and biologically, non-Hodgkin lymphoma (NHL) is characterized by the absence of Reed-Sternberg cells, can occur at any age, and usually presents as a localized or generalized lymphadenopathy associated with fever and weight loss. "Taken together, FTL004 distinguishes it from other CD38 targeting mAbs and represents a potential candidate for the treatment of MM and non-Hodgkin lymphoma." (PMID 36581954, 2022). "The efficacy of an anti-CD38 IB4/saporin-S6 was evaluated in different CD38+ human cell lines and in CD38+ malignant cells from a non-Hodgkin lymphoma (NHL) patient." (PMID 24105401, 2013). "A novel two-step pretargeted RIT (pRIT) strategy, using a less immunogenic bispecific protein (028-Fc-C825) targeting both the CD38 antigen and the 90Y-DOTA ligand, along with 90Y-DOTA-biotin, significantly reduced tumor growth and prolonged survival in both MM and non-Hodgkin lymphoma (NHL) models." (PMID 39199666, 2024). "It is also present in acute lymphoblastic leukemia, AML, chronic lymphocytic leukemia, and non-Hodgkin lymphoma (NHL); however, no in-depth studies have been conducted to verify the positive expression of CD38 in BL." (PMID 31484540, 2019).
non-small cell lung carcinoma (11 papers, 2013 to 2024). A group of at least three distinct histological types of lung cancer, including non-small cell squamous cell carcinoma, adenocarcinoma, and large cell carcinoma. "CD38, a transmembrane glycoprotein, mediates immunosuppression in non-small cell lung cancer (NSCLC)." (PMID 38533509, 2024). "In a previous study on non-small cell lung cancer, invasive immune cells were significantly enriched in tumor tissues of patients, and there was a strong correlation between CD38 and PD-1 expression on CD8+ T cells in tumors." (PMID 34484331, 2021). "A recent study in non-small cell lung carcinoma (NSCLC) patients also showed that a higher level of tumor-infiltrating CD38+ CD8+ T cells is correlated with better survival outcomes." (PMID 38680487, 2024). "Our results suggest that CD38 and PD-L1 are co-expressed in NPC, and some studies suggest that CD38 is positively expressed in patients with non-small cell lung cancer under the condition of PD-L1 resistance." (PMID 36605482, 2023). "Additionally, in human non-small cell lung cancer (NSCLC) cell line A549 and HepG2, CD38 overexpression led to significant NAD+ depletion." (PMID 39852780, 2024). "Investigation of another combination, daratumumab (anti-CD38 mAb) with PD-1 or PD-L1 inhibitors, was abandoned based on the unsatisfying results from a phase 1b/2 LUC2001 study of atezolizumab with or without daratumumab for advanced or metastatic non-small-cell lung cancer (NCT03023423)." (PMID 34483944, 2021).
pancreatic cancer (11 papers, 2012 to 2024). "In line with this, a similar population of CD38+ CD101+ PD1+ CD8+ T-cells cells are associated with poor prognosis in pancreatic cancer." (PMID 34960140, 2021). "CD8+, CD101+ T-cells expressing CD38 and PD-1 have been associated with poor prognosis in pancreatic cancer." (PMID 32661823, 2021). "For example, PD-1+, CD38+ CD8+ T-cells in the setting of pancreatic cancer fail to respond to anti-PD-1 therapy." (PMID 34960140, 2021). "Although the role of CD19+CD24+CD38+ and CD19+CD24+CD27+ regulatory B cells have been investigated in patients with type 1 autoimmune pancreatitis, the specific mechanism of action of CD19 is yet to be determined in pancreatic cancer." (PMID 34737763, 2021). "Likewise, concurrent overexpression of CD38 and NAMPT inhibition had synergistic effect on growth suppression in pancreatic cancer, suggesting a critical dependence of cancers on NAD+ that may be explored therapeutically." (PMID 35677882, 2022).
periodontitis (11 papers, 2016 to 2025). An acute or chronic inflammatory process that affects the tissues that surround and support the teeth. "We have shown that stimulation of lymphocytes from a patient who suffered from periodontitis with P. gingivalis caused maturation of cells into antibody secreting, CD38-expressing plasma cells, 2–3 weeks after stimulation." (PMID 27612600, 2016). "Future studies need to determine if the inhibition of CD38 by 78c could reduce autoantibodies in collagen-induced arthritis mice and if treatment with 78c could alleviate bone loss in animals with arthritis or periodontitis." (PMID 39682719, 2024). "In summary, we also found that CD38 had the highest correlation with periodontitis among the 9 hub DEPs, which was used as the main variable of the disease classifier." (PMID 36016933, 2022). "In the present study, CD19+, CD24+, and CD38+ were used as markers to characterize Breg cells from peripheral blood of periodontitis patients." (PMID 32604936, 2020). "Besides, both gene expression level and protein expression level of CD38 were up-regulated in periodontitis, and this consistent expression trend also suggested it as a representative signature of periodontitis." (PMID 36016933, 2022). "IL-37-producing plasma cells (CD138+CD38+PIL-37) expressing IL-37 and IL-37/IL-35-coproducing plasma cells (CD138+CD38+PIL-35/IL-37) expressing both of them are denoted as IgG+ plasma cells, and reduce periodontitis by suppressing the loss of alveolar bone by blocking osteoclast formation." (PMID 34248996, 2021). "Peripheral blood from 55 patients with stage 2 periodontitis and 20 healthy controls was analyzed using flow cytometry to evaluate the frequency of CD19+CD24+CD38+ Breg cells." (PMID 32604936, 2020).
pneumonia (11 papers, 2021 to 2025). An acute, acute and chronic, or chronic inflammation focally or diffusely affecting the lung parenchyma, caused by an infection in one or both of the lungs (by bacteria, viruses, fungi, or mycoplasma.). "Especially patients treated with ani-CD38 antibodies had almost a 40% higher risk of pneumonia and severe pneumonia." (PMID 39518146, 2024). "We found the exhaustion of CD4+ TEM in patients with acute pneumonia accompanied with a decrease of CCR7+CD45RA+ naïve T cells (CD38+HLA‐DR+)." (PMID 34841705, 2021). "MM patients treated with anti‐CD38 agents are at higher risk of infectious complications, especially pneumonia not Varicella‐Zoster Virus‐related, without an associated higher mortality rate." (PMID 39034465, 2024). "Also, there was a significant increase in non-hematological adverse events, such as dyspnea (RR 1.72; 95% CI 1.38–2.13; p < 0.01) and pneumonia (RR 1.34; 95% CI 1.13–1.59; p < 0.01), in the group treated with anti-CD38 monoclonal antibody." (PMID 38672988, 2024).
Splenomegaly (11 papers, 2011 to 2025). Abnormal increased size of the spleen. "We found that categorical variables such as the splenomegaly, trisomy 12, CD38, and positive anti-EBV EA IgA were associated with time to first treatment." (PMID 26460692, 2015). "Also, the significant association between CD38 expression and splenomegaly, intermediate and high-risk disease was reported by some other studies." (PMID 32883360, 2020). "Conclusion, our study showed CD38+ was significantly associated with Splenomegaly." (PMID 31122288, 2019). "The percentage of CD34+CD38- stem cells at diagnosis was correlated significantly to clinical scores, WBCs count, BM blast cells %, splenomegaly, and BCR-ABL %." (PMID 34711000, 2021). "As expected in CVID, an increased frequency of activated CD8+ CD127− CD38+ T cells was verified in the terminally differentiated effector memory (TEMRA) subset in CVID individuals with splenomegaly." (PMID 27188997, 2016). "However, both WT and Cd38−/− recipients developed similar levels of splenomegaly as judged by a similar increase in the total number of splenocytes." (PMID 34504495, 2021). "All other factors, namely platelet count, TLC, PB and BM blast %, BM cellularity and lymphocyte%, IPT, lymphadenopathy, hepatomegaly, splenomegaly, molecular genetics, cytogenetic risk stratification, CD34+, CD34+/CD38-, CD4+/CD3+, CD8+/CD3+, CD4/CD8 ratio and MRD had no impact on PFS." (PMID 40940644, 2025). "Engrafted CMML#1-MN1 cells had a myeloid phenotype expressing CD33, CD38, and CD123, but lacked expression of lymphoid markers CD3 and CD19, and developed splenomegaly." (PMID 32576961, 2020).
Arthritis (10 papers, 2012 to 2025). Inflammation of a joint. "Cd38-deficient mice exhibit marked attenuation of arthritis as well as inhibition of proinflammatory cytokines, paralleled with decreased phosphorylation of NF-κB." (PMID 36591261, 2022). "In addition, an immunohistochemical analysis suggests that CD38‐positive plasma cells may be the best differentiating and diagnostic marker for early onset of arthritis." (PMID 41339282, 2025). "Related studies have demonstrated that the majority of circulating ICI drugs bind to T cells that exhibit typical ICI arthritis phenotypes, namely CD38 high expression and CD127 low expression T cells." (PMID 39122457, 2024). "In particular, patients with ICI arthritis show increased levels of CD38 and HLA-DR, along with decreased levels of CD127." (PMID 39122457, 2024). "CD38−/− mice display an ameliorated inflammatory response in arthritis and infection models." (PMID 29977153, 2018). "The findings indicated an increase in the levels of CD38 and HLA-DR expression in T cells of patients with ICI arthritis, along with a decrease in CD127 expression." (PMID 39122457, 2024). "Potential biomarkers in early arthritis include differential infiltration by CD22+ve B cells and CD38+ plasma cells in patients with early arthritis differentiating RA vs. non RA inflammatory arthritis." (PMID 30761301, 2019). "Synovial membrane activation of JUN N-terminal kinase is increased in early RA, but not in undifferentiated forms of arthritis, and CD22+ and CD38+ cells distinguish RA from other forms of arthritis." (PMID 33968950, 2021). "Five weeks following the onset of arthritis, BMDCs generated over 7 days were isolated from the WT and CD38−/− mice with or without collagen stimuli, and the expression of NF-κB in BMDCs was detected." (PMID 30949517, 2019). "It is, therefore, likely that the reduction in the number of iNKT cells observed in CD38 KO mice, that are not recovered during CIA development, eventually contribute to the development of a mild arthritis in CD38 KO." (PMID 22438945, 2012).
esophageal cancer (10 papers, 2016 to 2025). A primary or metastatic malignant neoplasm involving the esophagus. "It is noteworthy that CD19 on IgD+ CD38- was found to be causally related to esophageal cancer, colon cancer, and cancer of the small intestine." (PMID 38533503, 2024). "CD38-expressing bone marrow-derived suppressor cells promote tumor growth in an esophageal cancer mouse model." (PMID 38277205, 2024). "CD38 was found to play an important role in the immunosuppressive function of myeloid-derived suppressor cells (MDSC) in an esophageal cancer model." (PMID 35725444, 2022). "A recent study showed that a CD38 mAb released T‐cell suppression by CD38‐expressing myeloid‐derived suppressor cells (MDSCs) resulting in a decreased tumor growth rate in an in vivo model of esophageal cancer." (PMID 26864107, 2016). "Moreover, “CD28 on CD39+ activated Treg” was causally related to stomach cancer and esophageal cancer, while “CD19 on IgD+ CD38- naive” was found to be causally related to colon cancer and cancer of the small intestine." (PMID 38533503, 2024). "CD38, usually expressed on plasma cells and other lymphoid and myeloid cell populations, has been revealed to mediate immunosuppression as a tumor escape mechanism, and there is evidence for an unfavorable CD38 influence on tumor progression in esophageal cancer." (PMID 32255255, 2020). "CD27 on CD20- CD38- B cell, as a potential mediator, reduced the intensity of Smoking status: Never in preventing or inhibiting esophageal cancer (mediating effect: -4.12%)." (PMID 38601154, 2024). "In esophageal cancer, the accumulation of inflammation-derived secretory factors, including IL-6, Insulin-like growth factor-binding protein-3 (IGFBP-3), and CXC motif chemokine ligand 16 (CXCL16), results in the upregulation of CD38 in myeloid-derived suppressor cells (MDSCs)." (PMID 40382743, 2025).
gastric cancer (10 papers, 2015 to 2024). A primary or metastatic malignant neoplasm involving the stomach. "We have recently gathered evidence that suggests that the overexpression of some tight junction proteins in gastric cancer cells affects CD38-related FasL expression and activity on NK cells." (PMID 33727923, 2021). "Further, the previous studies had proposed that the impact of CD38 on immune cells is primarily mediated through the regulation of FasL expression; Alterations in CD38/FasL-mediated NK cell apoptosis have been reported in gastric cancer." (PMID 38463232, 2024). "IL-10-expressing CD24+CD38+ Bregs were characterized in gastric cancer (GC) patients." (PMID 33193391, 2020). "A comprehensive immunophenotype of gastric cancer cells using an antibody microarray showed a higher expression of B-cell markers, including CD19, CD38, and surface immunoglobulin (sIg), in patients with H. pylori-infected gastric cancer than in patients without infections." (PMID 36010915, 2022). "e.g., our preliminary data in stomach cancer-affected wall showed that MPO-positive cells were more numerous in the stomach wall close to cancer infiltration, whereas the number of CD38-positive cells was similar in the tissue localized close and distally from cancer." (PMID 30373200, 2018). "PBMCs from gastric cancer patients were stained with various combinations of monoclonal antibodies to proteins which have been suggested for use in identifying Bregs, including: CD5, CD1d, CD38, CD24, IgM, CD25, CD10, and CD21." (PMID 26378021, 2015).